LGI1 (leucine rich glioma inactivated 1)
Diseases named in the same sentence as LGI1 in open-access papers (continued):
Sharing a sentence is not in itself a finding about the gene and the disease.
epilepsy (95 papers, 2010 to 2025). A brain disorder characterized by episodes of abnormally increased neuronal discharge resulting in transient episodes of sensory or motor neurological dysfunction, or psychic dysfunction. "Given the strong association between LGI1 dysfunction and epilepsy, the identification of kanzonol B as a potent LGI1 ligand opens a new avenue for antiepileptic drug development." (PMID 41386826, 2025). "Very recently, a population-wide genomic study of 748 879 individuals identified a novel association of ADAM23 with epilepsy as LGI1." (PMID 40455867, 2025). "Feline limbic encephalitis or epilepsy displaying focal orofacial seizures in association with LGI1-antibodies was first reported in four cats in 2014, and observed in 26 animals in 2023." (PMID 39984138, 2025). "For example, the epilepsy-associated mutations in LGI1 often cluster in the LRR (leucine-rich repeat) domains or the EPTP repeats, which mediate protein–protein interactions." (PMID 41386826, 2025). "LGI1 is linked to epilepsy, a neurological disorder that can be caused by genetic mutations of genes regulating neuronal excitability (e.g. voltage- or ligand-gated ion channels)." (PMID 40601686, 2025). "Clinical features of patients with biallelic LGI1 variants are substantially severe, showing early death and/or global developmental delay and intellectual disability besides epilepsy." (PMID 40455867, 2025). "Autoimmune mechanisms represent a novel category for causes of seizures and epilepsies in humans, and LGI1‐antibody associated limbic encephalitis occurs in cats." (PMID 37232512, 2023). "Recently, the mutation of Lgi1 and the auto-antibody of Lgi1 have been reported to lead to neuronal diseases, such as seizure, epilepsy, and cognitive amnesia." (PMID 36503961, 2023). "LGI1 gene mutations are involved in an inherited form of epilepsy called autosomal dominant temporal lobe epilepsy (ADLTE)." (PMID 35984846, 2022). "More studies are needed to clarify the underlying mechanisms of the dysregulation observed in LGI1 LE patients but our results indicate that special attention should be given to the inhibition as a leading cause for epilepsy in these patients." (PMID 35984846, 2022). "It has now become a rather common practice to derive AE models by the knockout of genes, presumably associated with epilepsy—they are Lgi1 mice, Fmr1 strain, etc.." (PMID 36428502, 2022). "Unlike most proteins whose gene mutations are associated with the development of epilepsy, Lgi1 is a secreted protein, the ligand of ADAM22 and ADAM23 (disintegrin and metalloproteinase domain-containing proteins)." (PMID 36428502, 2022). "The variant p.Ala3234Val was located at epilepsy-associated repeat 1, which is a common domain that existed in proteins encoded by epilepsy-associated genes such as LGI1 and was proposed to play an important role in the pathogenesis of epilepsy." (PMID 35813073, 2022). "The dysfunction of the Lgi1 (leucine-rich repeat glioma-inactivated) protein, originally described as a suppressor of tumor growth and metastasis is associated with epilepsy in humans." (PMID 36428502, 2022). "In a mouse model of autosomal dominant lateral temporal epilepsy (ADLTE), loss of LGI-1 downregulated the expression of Kv1.2 channels thus enhancing neuronal excitability and causing epilepsy." (PMID 34576077, 2021). "LGI1 is a secreted protein ligand expressed primarily in the hippocampus, and its loss has shown to cause hippocampal hyperexcitability leading to fatal epilepsies in mice." (PMID 32783406, 2020). "Actually, a secretion-defective E383A mutant of LGI1 is recognized by the endoplasmic reticulum (ER) quality control machinery and prematurely degraded to cause epilepsy in a mouse model of ADLTE9." (PMID 29670100, 2018).
epilepsy (continued). "The absence of ligand–receptor interaction between LGI1 and ADAM22 was found to cause abnormal synaptic transmission and epilepsy in the LGI1 specifically disrupted mice." (PMID 28487693, 2017). "Here, we aimed to further get insight into the pathogenic mechanism underlying the origin of seizures in LGI1-related epilepsies, independently of circuit damage due to seizure occurrence." (PMID 26878798, 2016). "Together these observations underscore an important role for LGI1 in brain excitation and development, explaining why LGI1 mutations result in epilepsy." (PMID 23713523, 2013). "The final phenotype is the intractable and fatal mid-pruning phase-onset murine epilepsy caused by complete LGI1 deficiency." (PMID 21829378, 2011). "In summary, wt LGI2 binds the same ADAM substrates of LGI1 following secretion, and the Lagotto K518X mutation prevents secretion and ADAM interaction, in the same fashion as the well-characterized truncating LGI1 epilepsy mutations." (PMID 21829378, 2011). "The underlying mechanism behind the genetic predisposition to epilepsy conferred by mutations in the Lgi1 gene is still poorly understood." (PMID 21569517, 2011). "Mutations in the Leucine-rich, glioma inactivated 1 (LGI1) gene predispose to a hereditary form of epilepsy known as autosomal dominant partial epilepsy with auditory features (ADPEAF)." (PMID 22053218, 2011). "In addition to Streptococcus, the taxa Enterococcus41 and Roseburia42 have been found to be associated with intractable childhood or drug‐resistant epilepsy (respectively), and Roseburia in another study of LGI1‐Ab‐E,43 matching our case subtype." (PMID 40768327, 2025). "Further experimental studies are crucial to validate the functional effects of Kanzonol B on LGI1 in cellular and animal models of epilepsy, particularly those linked to LGI1 dysfunction, and to determine its precise mechanism of action in modulating LGI1-mediated synaptic transmission." (PMID 41386826, 2025). "Moreover, they demonstrated that an improvement of LGI1 secretion by 4PBA, a chemical corrector, reduces the risk of developing epilepsy in mouse with LGI1 secretion-defective mutations." (PMID 36804022, 2023). "Mutations in the Lgi1 gene leading to epilepsy cause impaired secretion of the Lgi1 protein." (PMID 36428502, 2022). "We identified a novel epilepsy‐causing mutation of LGI1 in humans." (PMID 34767694, 2022). "LGI1 has been reported associated with the etiology of epilepsy." (PMID 33287870, 2020). "LGI1 is an epilepsy-related gene that encodes a secreted neuronal protein." (PMID 29670100, 2018). "Lig1 has been documented as an epilepsy-linked gene because Lgi1 mutations result in ADLTE." (PMID 30034322, 2018). "Interestingly, ARX is an another epilepsy-related gene encoding a transcription factor which regulates LGI1 expression." (PMID 26878798, 2016). "Moreover, it was demonstrated that the loss of LGI1 gene in mice induced lethal epilepsy, suggesting its essential role as an antiepileptogenic ligand." (PMID 27064559, 2016). "We previously reported NgR1 as receptor for the epilepsy‐linked protein LGI1." (PMID 27468420, 2016). "Should pathogenic anti-LGI1 antibodies bind to specific epitopes, these epitopes could be druggable and lead to effective new epilepsy treatments." (PMID 23713523, 2013). "A completely independent line of inquiry implicated LGI1 in epilepsy." (PMID 23713523, 2013). "ADAM23 binds two epilepsy-associated proteins, LGI1 and LGI2." (PMID 22457775, 2012). "The resulting epilepsy onsets at around seven weeks (equivalent to human two years), and remits by four months (human eight years), versus onset after age eight in the majority of human patients with LGI1 mutations." (PMID 21829378, 2011). "How these secretion-defective LGI1 mutations lead to epilepsy is unknown." (PMID 36804022, 2023). "•Anti-LGI1 associated epilepsy may particularly respond to sodium channel blocking AED." (PMID 32480242, 2020).
epilepsy (continued). "Mutation in LGI1 could cause epilepsy, familial temporal lobe, 1 (OMIM:600512)." (PMID 33287870, 2020). "Consequently, LGI1 may be an essential cause of brain excitation, and the LGI1 gene-targeted mouse is a promising model for human epilepsy." (PMID 31540204, 2019). "Further, we observed epileptic discharges from the isolated whole hippocampus of Lgi1–/– knockout mice, experimentally modelling the hippocampal origin of LGI1-related epilepsy." (PMID 40455867, 2025). "If LGI1 is knocked out globally, synaptic transmission is disrupted and neuronal excitability is altered, resulting in autonomous epilepsy and pre-mature death in mice." (PMID 36804022, 2023). "One of the possible mechanisms explaining the relationship between LGI1 inactivation and epilepsy is deletion of chromosome 10q24, where the LGI1 gene is located." (PMID 38067243, 2023). "In anti-LGI-1 encephalitis presenting epilepsy, levels of NF-L were enhanced further compared to cases without epilepsy." (PMID 36884195, 2023). "Recent examples of chemical chaperones for genetic epilepsies include studies of Munc18-1 related epilepsy and LGI1-related epilepsy, which we will discuss next." (PMID 35250833, 2022). "The first group is the studies that described the generation of patient-specific iPSC lines that carry genetic variants in genes associated with epilepsy, such as SCN1A, GNB5, LGI1, GRIN2A, KCNC1, or KCNA2." (PMID 36552721, 2022). "LGI1 is mainly expressed in hippocampus and neocortex which is a transsynapsin secretory protein, it connects presynaptic epilepsy-related ADAM23 to postsynaptic ADAM22." (PMID 36316880, 2022). "Here, we enrolled 33 anti‐LGI1 AE patients in our tertiary epilepsy center, and they all had seizures during the long‐range video EEG examination." (PMID 34291554, 2021). "Remarkably, in the brain, extracellular LGI1 simultaneously binds postsynaptic ADAM22 and presynaptic ADAM23, two epilepsy-associated syndrome receptors." (PMID 31540204, 2019). "This study thus reveals an unexpected likely mechanism of epileptogenesis involved in LGI1-related epilepsies." (PMID 26878798, 2016). "ADAM23 plays a role in synaptic transmission and interacts with known epilepsy genes, LGI1 and LGI2, and should be considered as a candidate gene for human epilepsies." (PMID 26084559, 2015). "Although LGI1 is shown to be correlated with epilepsy, its precise functions in the CNS are still poorly understood." (PMID 25591666, 2015). "Leucine-rich glioma inactivated 1 (LGI1) is a secreted protein that interacts with ADAM transmembrane proteins, and its mutations are linked to human epilepsy." (PMID 25591666, 2015). "LGI1 antibodies have been detected predominantly in limbic encephalitis, epilepsy and few patients with Morvan’s disease." (PMID 24950993, 2014). "Both ADAM22 knockout and ADAM23 knockout mice show strong overlap in phenotype with LGI1 knockout mice, which is characterized by severe spontaneous epilepsy and premature death." (PMID 23713523, 2013). "Similar mutations truncating LGI1 in the EPTP repeats in humans, including in the seventh repeat, cause ADLTE, the human epilepsy with most commonly onset after age eight and persistence through adulthood." (PMID 21829378, 2011). "Two other loci, both human epilepsy-associated genes, though insignificant, had lower p-values: KCNQ3 at 0.077 and LGI1 at 0.070." (PMID 21518446, 2011). "Following the line of evidence presented in this paper and collected from previous reports, we arrive at the conclusion that LGI1 and LGI2 apparently share the cellular mechanism of causing genotypically distinct but phenotypically related forms of epilepsy." (PMID 20863412, 2010). "Feline LGI1-Ab-E represents a clinically distinctive seizure disorder." (PMID 39984138, 2025).
epilepsy (continued). "Despite a variety of neurological symptoms in LE, no LGI1 variants related to neurological symptoms besides pure epilepsy have been reported." (PMID 40455867, 2025). "Kir4.1 expression is also significantly reduced in NER and Lgi1 genetic epilepsy model rats." (PMID 40170730, 2025). "Given the role of LGI1 in regulating excitability in relationship to epilepsy within the nervous system, we next investigated whether neuron activity in pain circuits was altered in our conditional LGI1 knockout lines." (PMID 39301592, 2025). "Because LGI1 is highly expressed in the hippocampus, we examined whether the hippocampus is the epileptic focus of LGI1-related epilepsy." (PMID 40455867, 2025). "Furthermore, the expression of LGI1, a human-epilepsy related gene, was significantly lower in the epileptic hippocampus compared to the autoptic samples (P ≤ 0.05)." (PMID 37658249, 2024). "Furthermore, enhancing the interaction between the LGI1-ADAM22 complex and PSD-95 family proteins may prevent epilepsy, and restoring Kv1 activity using celecoxib, a drug approved by the Food and Drug Administration, ameliorates seizure susceptibility in global LGI1 knockout mice." (PMID 36804022, 2023). "We specifically expressed mutant LGI1W183R in excitatory neurons lacking natural LGI1, and found that this mutation downregulated Kv1.1 activity, led to neuronal hyperexcitability and irregular spiking, and increased epilepsy susceptibility in mice." (PMID 36804022, 2023). "In contrast, monoallelic variants in LGI1 cause therapy-responsive, mild epilepsy, but individuals with biallelic LGI1 variants have not been reported, probably due to their lethality." (PMID 35373813, 2022). "Anti‐LGI1 AE patients were retrospectively screened between May 2014 and September 2019 in our tertiary epilepsy center." (PMID 34291554, 2021). "This study retrospectively analyzed 33 anti‐LGI1 AE patients in our tertiary epilepsy center." (PMID 34291554, 2021). "Leucine-rich glioma-inactivated 1 (LGI1) proteins are involved in tumor suppression and epilepsy." (PMID 32775036, 2020). "LGI1 is associated with both human and animal epilepsy, and it is a neuronal secreted protein not encoding a subunit of the ion channel." (PMID 31540204, 2019). "Thus, it seems possible that the down-regulation of astrocytic Kir4.1 channels participates in the development of epilepsy in Lgi1 mutant rats." (PMID 30813600, 2019). "LGI1 antibodies are involved in limbic encephalitis (over 90%), but a small part of patients may develop epilepsy, a subacute encephalopathy, or Morvan syndrome." (PMID 31540204, 2019). "Other known epilepsy genes affected by deletions include LGI1 and the 15q13.3 region." (PMID 29649218, 2018). "Some other epilepsy-related mutations have been found in genes encoding non-ion channel proteins such as LGI1." (PMID 29670100, 2018). "Here the authors present the crystal structure of LGI1 bound to its receptor ADAM22, which provides structural insights into epilepsy-causing LGI1 mutations and might facilitate the development of novel anti-epilepsy drugs." (PMID 29670100, 2018). "In addition to FBDS, several other focal seizure semiologies are recognised in patients with LGI1 antibodies and are relatively infrequent in other seizure disorders." (PMID 29055902, 2018). "Animal studies have shown that lack of LgI1 causes lethal epilepsy and that LgI1 regulates excitability in the brain." (PMID 28442990, 2017). "LGI1 is aunique human epilepsy-related gene that does not encode an ion channel subunit, butis a neuronally secreted protein." (PMID 29213481, 2016). "In a transgenic mouse model of epilepsy expressing a secretion-defective mutant form of human LGI1, intraperitoneal injection of 4PBA restored the binding of mutant LGI1 protein to its receptor ADAM22 and prevented the increased seizure susceptibility of the mouse model." (PMID 27519691, 2016).
epilepsy (continued). "By extension, the presence of serum LGI1 or CASPR2-antibodies in unselected patients with epilepsy of unknown aetiology may be sufficient evidence to prompt ITs, and in two studies this approach was employed with some benefits." (PMID 27450643, 2016). "LGI1 may serve as a major determinant of brain excitation and the LGI1 gene-targeted mouse could provide a good model for human epilepsy." (PMID 27064559, 2016). "LGI1, ADAM22, and ADAM23 are all genetically linked to epilepsy." (PMID 27066583, 2016). "A reduction in the ADAM23-mediated LGI1-stimulation of neurite outgrowth in the central nervous system was suggested to contribute to epilepsy, although other yet unknown ADAM-LGI-mediated alterations may exist." (PMID 26084559, 2015). "Therefore, it is possible that, in addition to epilepsy, LGI1 is involved in nuclear mitogenic signaling, migration and morphology, and cell differentiation in the CNS." (PMID 25591666, 2015). "Thus, the identification of a connection between LGI1 and LE will advance both our understanding of synaptic biology, and our approach towards diagnosis and treatment of epilepsy." (PMID 23713523, 2013). "ADAM23 interacts with known epilepsy proteins LGI1 and LGI2." (PMID 22457775, 2012). "Humans not expressing or secreting LGI1 from one allele develop epilepsy starting in the vast majority of cases after age eight and seeming to persist in adulthood in many cases." (PMID 21829378, 2011). "Future directions could implement joint human-feline patient video rating studies, and characterise other relevant phenotypic aspects of LGI1-Ab-E in cats, including cognitive and behavioural impairments, as well as screening in a more general feline epilepsy cohort." (PMID 39984138, 2025). "*Autoimmune epilepsy antibody panel includes CASPR2 (contactin-associated protein-like 2), GAD65 (glutamic acid decarboxylase 65), VGKC (voltage-gated potassium channel), LGI1 (leucine-rich glioma-inactivated 1), and NR1 (NR1 subunit of the N-methyl-D-aspartate (NMDA) receptor) antibodies." (PMID 41200626, 2025). "Additionally, some epilepsy-related mutations have been identified in genes encoding non-ion channel proteins such as LGI1." (PMID 40601686, 2025). "However, it is possible that the reduced LGI1 expression in epileptogenic gliomas stems from the frequent deletion of the 10q chromosome and is not directly associated with epilepsy." (PMID 38067243, 2023). "Although the expression of LGI1 decreases in gliomas with increasing malignancy and there is a potential association between tumours and epilepsy, there is currently no available evidence to support this hypothesis." (PMID 38067243, 2023). "In addition to identifying LGI1-related epilepsy as a conformational disease, this study suggests a bright future for chemical chaperones as a precision therapy for certain monogenic epilepsies." (PMID 35250833, 2022). "Hence, this functional LGI2-to-LGI1 transition may explain the benign and remitting course of epilepsy in the Lagotto Romagnolo breed." (PMID 26316206, 2015). "LGI1 mutations do not appear to affect depression independently of epilepsy." (PMID 23713523, 2013). "Thus, Lgi1 represents the only hereditary epilepsy predisposition gene which is not a channelopathy and offers the opportunity to understand different mechanisms behind seizures in these individuals." (PMID 21569517, 2011). "Thus, LGI1 is the first epilepsy predisposing gene that does not encode a structural component of an ion channel." (PMID 22053218, 2011). "Experimental testing of cellular effects of mutations in both LGI1 and LGI2 reported in this work results in an effective doubling of experimentally characterized mutations in LGI proteins and, hence, generally advances our understanding of molecular disease mechanisms of LGI-related epilepsies." (PMID 20863412, 2010).